ALK (ALK receptor tyrosine kinase)
Diseases named in the same sentence as ALK in open-access papers (continued):
Sharing a sentence is not in itself a finding about the gene and the disease.
cancer (continued). "The CCLE database that has fusion data for multiple cancer lines including CCA lines show that KKU-213 and RBE do not present with ALK fusions." (PMID 38144528, 2023). "A direct comparison with the cancer genome atlas (TCGA) adult series cannot be made, but it is worth noting that NTRK3 rearranged PTCs, as well as ALK and NTRK1, were not consistently and homogeneously defined as BRAF-like or RAS-like tumors." (PMID 34206589, 2021). "Anaplastic Lymphoma Kinase (ALK) is an activator of the PI3K/AKT signaling pathway, and it induces phosphorylation of the p55γ subunit of PI3K in cancer cells, rather than the usual p85 subunit that is phosphorylated." (PMID 34925334, 2021). "ALK rearrangement was only observed in patients with C-LCNEC, and we did not detect alterations in other driver genes for both carcinoma types." (PMID 34631540, 2021). "Between 2002 and 2018, a total of twelve ALK-negative and CD30-positive ALCL were identified by our cancer registry." (PMID 32344893, 2020). "Lorlatinib serves as an ATP-competitive TKI for both ALK and ROS1, an RTK in the insulin receptor family with striking similarity to ALK that is overexpressed in several cancer types, but absent in normal lung tissue." (PMID 29973561, 2018). "At the present time, ALK inhibitors have not yet been approved for use in other ALK-driven cancers than NSCLC; however, some studies have reported remarkable responses, and less frequent relapses, to ALK inhibitors in patients with ALK-positive ALCL and IMT." (PMID 29495603, 2018). "Collectively, these findings support a potential role for MIR503HG in cancer cell proliferation through the miR-503/Smurf2/TGFBR axis and indicate that MIR503HG is a potential marker in ALK-negative ALCL." (PMID 29758012, 2018). "Moreover, in cancer-related nonhistone methylation, SMYD2 methylates the RB1, ALK, and β-catenin proteins to regulate the cell cycle and cell proliferation, implying that SMYD2 is a potential therapeutic target for cancer treatment." (PMID 37121971, 2023). "The results of the driver gene detection for EGFR, ALK, and ROS1 in cancer cells from peripheral blood samples were negative (May 15, 2021)." (PMID 35029237, 2022). "Interestingly, ROS1 and BRD4 KGFs occur at four different breakpoint sites; conversely, ALK and RET are found rearranged using the same breakpoint in different cancer cell line models, regardless of the cancer type context." (PMID 33257674, 2020). "Moreover, although the expression of ALK and ROS1 at the C-terminus was very limited in all fusion-negative cancer cells, the expression or phosphorylation of C-terminal RET was markedly elevated in 2 of the 36 RET fusion–negative cancer cells." (PMID 30943926, 2019). "Taken together, the results suggest that crizotinib is effective for treating ALK-driven cancer and might be a new therapeutic drug, without cardiac or respiratory muscle toxic effects, for TPM4-expressing cancers." (PMID 31278140, 2019).
adenocarcinoma (536 papers, 2010 to 2026). A common cancer characterized by the presence of malignant glandular cells. "clinical prioritization of detecting actionable driver mutations (e.g., EGFR, ALK) for guiding first-line therapy, particularly in adenocarcinoma; c." (PMID 41002559, 2025). "Epidermal growth factor receptor (EGFR) mutations and anaplastic lymphoma kinase (ALK) fusions were found to be specific to TRU-type adenocarcinomas." (PMID 38710944, 2025). "Approximately 3–5% of NSCLC tumors harbor rearrangements of the anaplastic lymphoma kinase (ALK) gene, which defines a distinct molecular subtype primarily associated with adenocarcinoma histology." (PMID 40416880, 2025). "EGFR mutations were most common (35.9%), followed by ALK rearrangements (14.2%), especially in adenocarcinoma group (p < 0.001)." (PMID 41002559, 2025). "For example, some studies suggest that the signet ring morphology of the adenocarcinoma is associated with ALK rearrangement, which benefits from tailored therapy with ALK-tyrosine kinase inhibitors (ALK- TKI)." (PMID 38256374, 2024). "This article accurately diagnoses and retrospectively analyzes the clinical data of a case of ALK mutant adenocarcinoma in a male patient who developed an EGFR mutation with multiple metastases four years after surgery, and reviews the relevant literature." (PMID 39147711, 2024). "Still, ALK gene rearrangement was reported in some NSCLCs; its prevalence is between 3% to 7% in adenocarcinoma cases; many current diagnostic protocols include routine ALK testing for relevant histology samples." (PMID 36979684, 2023). "Patient 4 was a 29-year-old woman with an ALK-mutated stage IIIa (cT2aN2M0) acinar-predominant adenocarcinoma." (PMID 39790537, 2023). "In the adenocarcinoma group, the main mutations were ALK (Ile1461Val), in 95.24% of patients, EML4 (Lys398Arg) in 47.62% of the patients, and EGFR (Arg521Lys) and ROS (Arg167Gln) in 42.86% of the patients." (PMID 36422072, 2022). "Here, we present the case of a 37-year-old female who was diagnosed with stage IV NSCLC (adenocarcinoma) with a positive ALK mutation six years ago." (PMID 35165619, 2022). "Regarding the adenocarcinoma group, the main mutations were ALK (Ile1461Val) in 95.24% of patients, EML4 (Lys398Arg) in 47.62% of the patients, and EGFR (Arg521Lys) and ROS (Arg167Gln) in 42.86% of the patients." (PMID 36422072, 2022). "Approximately 3–7% of patients with NSCLC, especially for those with the adenocarcinoma subtype, have been reported to harbor ALK rearrangements; ALK mutations are mutually exclusive with KRAS and EGFR mutations." (PMID 36224343, 2022). "ALK rearrangement is generally correlated with adenocarcinoma histology and patients with this gene mutation are mostly younger, with light- or never-smoking history." (PMID 36230686, 2022). "The aim of this study was to identify the relationships of epidermal growth factor receptor (EGFR) mutations and anaplastic large-cell lymphoma kinase (ALK) status with CT characteristics in adenocarcinoma using the largest patient cohort to date." (PMID 33707479, 2021). "One study reported that specimens obtained via RP‐EBUS‐TBLB using a 1.8‐mm diameter biopsy forceps allowed analyses of EGFR mutational status, and ALK and PD‐L1 IHC, in more than 90% of adenocarcinoma cases." (PMID 33949136, 2021). "Regarding EGFR mutation and ALK translocation in adenocarcinoma, seven cases were L858R positive, three cases were exon 19 positive, one case was ALK positive, and 12 cases were wild type." (PMID 35201464, 2021). "Improvements in histological classifications and diagnostic techniques, especially of adenocarcinoma in concert with the identification on specific oncogenic factors (EGFR mutations or rearrangements of the ALK) have been suggested to affect their increase." (PMID 34857781, 2021). "Ten patients had epidermal growth factor receptor (EGFR)-mutated and one had anaplastic lymphoma kinase (ALK)-rearrangement adenocarcinomas." (PMID 33228799, 2020).
adenocarcinoma (continued). "Currently, it is recommended that all NSCLC patients with an adenocarcinoma component are tested for ALK rearrangements in their diagnostic biopsy, and several ALK TKIs are approved for the treatment of ALK-positive patients." (PMID 32290439, 2020). "Especially, it makes difficult to assess the PD-L1 positivity in adenocarcinoma showing ALK-positive-associated histologic features such as mucinous cribriform pattern." (PMID 31561631, 2019). "Intracellular mucin vacuoles are frequently observed in ALK-rearranged adenocarcinoma; thus, inadequate cytoplasmic immunostaining can cause these to be carelessly missed." (PMID 29538329, 2018). "Testing for ALK mutation was performed in 32 patients with adenocarcinoma of whom two (6.25%) were found to be positive." (PMID 29094084, 2017). "Another therapeutic target, the echinoderm microtubule-associated protein like 4(EML4)-anaplastic lymphoma kinase (ALK) fusion protein, has also been uniquely detected in a subset of adenocarcinomas." (PMID 25977750, 2015). "In this study, we investigated the frequencies and clinicopathological characteristics of driver mutations, focusing on ALK rearrangement in resected adenocarcinoma with GGO patterns." (PMID 24885886, 2014). "The prevalence of EGFR and ALK mutations in GGO nodules in this study was compared to previous reports of adenocarcinoma of all types." (PMID 24885886, 2014). "In contrast, the most recent NCCN guidelines (version 1.2012) recommend ALK rearrangement testing concurrent with EGFR mutation testing for adenocarcinomas, large cell carcinomas and NSCLC NOS." (PMID 22825000, 2012). "There are therapies that target EGFR mutations and ALK fusion genes which are found almost exclusively in adenocarcinomas." (PMID 23190601, 2012). "Results showing that ALK fusion is frequently associated with adenocarcinoma and younger onset of disease were consistent with previous reports." (PMID 20624322, 2010). "However, it is also known that brain metastasis-associated edema is more aggressive in adenocarcinoma patients with mutations such as EGFR or ALK when compared to other NSCLC types." (PMID 40428276, 2025). "However, prolonged survival has been reported in patients with symptomatic bone marrow metastasis from EGFR‐, ERBB2‐ mutated or ALK fusion—positive adenocarcinoma treated with tyrosine kinase inhibitors." (PMID 41314797, 2025). "However, the specific imaging and pathological features of EGFR and ALK gene mutations in adenocarcinoma are still controversial." (PMID 35340157, 2022). "The EGFR and ALK genes mutated adenocarcinomas have specific imaging and clinicopathological features, and the mutations in exon 19 or exon 21 subtype have different imaging features, which is of great significance in guiding the clinical diagnosis and treatment of pulmonary nodules." (PMID 35340157, 2022). "Therefore, it is critical to determine EGFR mutation and ALK statuses prior to the use of TKIs in patients with adenocarcinoma." (PMID 33707479, 2021). "Ten patients had EGFR-mutated and one had ALK-rearrangement adenocarcinomas." (PMID 33228799, 2020). "Although targeted therapy against adenocarcinoma with epidermal growth factor receptor (EGFR) gene mutation or anaplastic lymphoma kinase (ALK) and ROS1 proto-oncogene receptor tyrosine kinase (ROS1) rearrangements have shown dramatic effects, few targeted therapies against SCC have been identified." (PMID 31481045, 2019). "Detailed pathologic examination of the ERβ-positive adenocarcinoma may be necessary to show the genotype-phenotype correlations, similar to those found in the ALK-rearranged or the EGFR-mutated adenocarcinoma." (PMID 28783064, 2017).
adenocarcinoma (continued). "Notably, the presence of ALK fusions was associated with histological adenocarcinomas and with wild-type EGFR and KRAS status, which may be of clinical relevance in targeted therapy using ALK inhibitors." (PMID 20624322, 2010). "Cytology of the effusion confirmed adenocarcinoma cells and was positive for ALK by immunohistochemistry." (PMID 41497773, 2026). "Given that the patient has mixed histologies of ALK-rearranged adenocarcinoma and small cell carcinoma, he has tolerated lorlatinib well with no notable toxicities reported." (PMID 41584719, 2026). "A biopsy of the right lower lung lesion in February confirmed adenocarcinoma and was again positive for ALK fusion." (PMID 41497773, 2026). "Experience with IO alone or in combination with chemotherapy (CT) is limited in transformed-ALK patients, and to date, there are no studies evaluating the role of CT and IO in patients with SCLC transformed from adenocarcinoma with ALK translocation." (PMID 40507907, 2025). "A study of 102 cases of LCLC revealed that adenocarcinoma-associated mutations (EGFR, KRAS, BRAF, and ALK) occurred exclusively in the null immunophenotype or adenocarcinoma-differentiated LCLC." (PMID 40898486, 2025). "Pathologic assessment confirmed a poorly differentiated adenocarcinoma that tested positive for an ALK fusion using the 5A4 immunohistochemical clone that was standard of care for ALK testing at that time." (PMID 40422509, 2025). "An updated analysis for patients treated from 2006 to 2014, which included EGFR and ALK status, showed improved survival up to 12 months overall with 15.2 months for adenocarcinoma and 9.2 months for non-adenocarcinoma patients." (PMID 40427102, 2025). "According to the crizotinib patient database, adenocarcinoma made up 97 percent of 255 cases with an ALK fusion oncogene presence." (PMID 40332427, 2025). "ALK fusion-positive adenocarcinoma showed a similar pattern (49.1 vs. 40.3 months; HR 0.69, 95% CI: 0.49 –0.97, p = 0.034)." (PMID 40940992, 2025). "In adenocarcinoma, tyrosine kinase inhibitors were developed for EGFR mutations and ALK and ROS1 translocations and were approved for use in the treatment of advanced stage adenocarcinomas." (PMID 40076671, 2025). "Survival analysis demonstrated that younger age, female sex, adenocarcinoma histology, p-stage II, low CD score, positive EGFR/ALK mutation, and ICI were associated with better OS in those who treated with adjuvant chemotherapy by univariate analysis." (PMID 40676423, 2025). "In contrast, adenocarcinoma with ALK rearrangement demonstrated mostly IE-TME, with few cases having Inflamed TME." (PMID 40809430, 2025). "Rebiopsy (bronchoscopy) 16/08/2023 (HP + IHC + Genetic tests: poorly differentiated adenocarcinoma; ALK, EGFR, PD-L1 positive) low expression (TPS = 5%)." (PMID 40429388, 2025). "Adenocarcinoma is often associated with genetic mutations such as EGFR (epidermal growth factor receptor), ALK (anaplastic lymphoma kinase), and KRAS (Kirsten rat sarcoma viral oncogene homolog), making it a target for precision therapies." (PMID 40728967, 2025). "Twenty-five patients had adenocarcinoma (89.3%), six had EGFR mutations (21.4%) and two had ALK mutations (7.1%)." (PMID 39445449, 2024). "Molecular and clinical studies of NSCLC have identified functional mutations in tyrosine kinase (TK) receptors such as anaplastic lymphoma kinase (ALK), present in ~7% of adenocarcinoma tumors that can be used in targeted therapy." (PMID 38319906, 2024). "As well, histological types other than adenocarcinoma and ALK rearrangements were infrequent in the included population." (PMID 39267111, 2024). "Genetic variations that are frequently detected in adenocarcinoma include EGFR, ALK, and ROS1 mutations." (PMID 39685930, 2024). "Conversely, ALK inhibition or depletion selectively affected the control of ERα levels and cell proliferation in LumB, adenocarcinoma, PR-negative, and HER2-positive MDA-MB-361 cells." (PMID 38589728, 2024).
adenocarcinoma (continued). "The percentage of patients with a high CYFRA21‐1:CEA ratio was also significantly higher in the ALK group (28%) compared with the EGFR group (14%) in cases restricted to adenocarcinoma (p = 0.004)." (PMID 38400801, 2024). "EGFR mutations, ALK, and ROS1 translocations were identified almost exclusively in patients with adenocarcinoma in line with reported scientific literature." (PMID 39512773, 2024). "Guidelines from prominent medical organizations recommend analyzing adenocarcinoma tumors or metastases for EGFR and ALK mutations, particularly in patients with a history of light or never smoking." (PMID 39429333, 2024). "The same analysis was done for the adenocarcinoma cases, in which 96 patients received ALK–TKIs and 135 patients received EGFR–TKIs." (PMID 38400801, 2024). "The same trend was observed for the adenocarcinoma cases (0.333 in the ALK group and 0.101 in the EGFR group; p < 0.001)." (PMID 38400801, 2024). "Guidelines recommend testing for driver mutations (e.g., EGFR, ALK, ROS1) in advanced NSCLC, particularly adenocarcinoma." (PMID 39429333, 2024). "ALK rearrangements occur in about 5–8% of adenocarcinoma cases but are responsive to ALK inhibitors in various clinical trials, improving the median progression-free survival in patients." (PMID 38927911, 2024). "All NSCLC tissues evaluated in our study were ALK-rearranged adenocarcinoma, and only a few patients were current smokers, possibly explaining the beneficial effect of a higher BMI." (PMID 37444532, 2023). "On this basis the present review describes the therapeutic strategies integrating medical and radiation oncology in patients with metastatic NSCLC (mNSCLC) adenocarcinoma with CNS involvement and EGFR activating mutations or ALK rearrangement." (PMID 36786970, 2023). "The most common histology was adenocarcinoma (78.2%), and driver‐gene mutations were observed in 9 patients (8 EGFR+, 1 ALK+)." (PMID 37076988, 2023). "This is in alignment with the evidence of higher BrMs rates in adenocarcinoma subtype, especially in those harboring targetable mutations, such as EGFR and ALK rearrangements." (PMID 37035171, 2023). "Mean (standard deviation [SD]) age for 1073 patients with EGFR-wild-type/ALK-wild-type mNSCLC was 66.2 (8.9) years, 65.2% were male and 63.7% had adenocarcinoma." (PMID 37386452, 2023). "In contrast to better-known driver alterations in adenocarcinoma, such as EGFR, KRAS, and ALK, passenger mutations seem to contribute to the high somatic mutation rate in LUSC." (PMID 36873930, 2023). "The clinical features of ALK+ NSCLC are an adenocarcinoma histology, younger age, limited smoking history, and brain metastases." (PMID 37232842, 2023). "Most prevalent actionable mutations in adenocarcinoma include KRAS, EGFR, ALK, RET, ROS1, BRAF, HER2, MET." (PMID 37301854, 2023). "The most common histological subtype was adenocarcinoma [98 (86.0%)]; 33 (28.9%) patients harbored a sensitive EGFR mutation (del exon 19 or L858R) or an ALK rearrangement." (PMID 37916162, 2023). "EGFR and ALK mutation testing is suggested for patients with NSCLC, adenocarcinoma, and large-cell carcinoma by the National Comprehensive Cancer Network Clinical Practice Guidelines in Oncology." (PMID 36290461, 2022). "We present a case of a 17‐year‐old male with metastatic treatment‐naïve ALK‐positive adenocarcinoma." (PMID 35092185, 2022). "EGFR (Arg255Gln), EGFR (Ala647Thr), EGFR (Leu858Arg), KRAS (Gly12Cys), ALK (Pro254Thr), ALK (Trp288Ser), ALK (Glu797Lys), ROS (Glu1902Lys), PIK3CA (Met1043Ile), ROS (Leu567Val), and ROS (Phe1153Leu) mutations were present only in patients with adenocarcinoma." (PMID 36422072, 2022). "Well-established actionable targets in adenocarcinoma include mutations in the gene encoding epidermal growth factor receptor (EGFR, 9%), anaplastic lymphoma kinase (ALK, 3.9%), c-ros oncogene 1 (ROS1, 1%) and B-type Raf proto-oncogene (BRAFV600E, 1%)." (PMID 35743191, 2022).